TLN1 (talin 1)
Diseases named in the same sentence as TLN1 in open-access papers (continued):
Sharing a sentence is not in itself a finding about the gene and the disease.
Cognitive impairment (1 paper, 2017). Abnormal cognition is characterized by deficits in thinking, reasoning, or remembering. "THBS4 and Talin-1 were also both validated using ELISA as being significantly upregulated in the TBI patients with cognitive impairment." (PMID 28251161, 2017). "However, the impact of Talin-1 on TBI-induced cognitive impairments has yet to be unravelled." (PMID 28251161, 2017). "Talin-1, which is the key talin member in immune cells, was found to be significantly upregulated in the TBI patients with cognitive impairments as compared to the negative and HC subjects." (PMID 28251161, 2017).
colonic disease (1 paper, 2023). "Here we show that mice lacking talin-1 in intestinal epithelial cells (Tln1Δepi) have heightened susceptibility to colonic disease caused by the A/E murine pathogen Citrobacter rodentium." (PMID 36951501, 2023).
coronary atherosclerosis (1 paper, 2020). Atherosclerosis of the coronary vasculature. "Therefore, high sTalin-1 levels in patients with CAD may reflect inflammation in coronary atherosclerosis or represent an adaptive response to low talin-1 expression in coronary atherosclerotic plaques." (PMID 32566035, 2020).
cutaneous melanoma (1 paper, 2023). A primary melanoma arising from atypical melanocytes in the skin. "The results of the TCGA database via GEPIA2 revealed that mRNA expression of the Talin-1 gene was higher (|Log2FC| Cut-off ≥ 0.5) in 461 skin cutaneous melanoma tissues compared to the 558 normal skin tissues (P < 0.01)." (PMID 37013489, 2023).
dental caries (1 paper, 2021). The decay of a tooth, in which it becomes softened, discolored, and/or porous. "Neither TLN1 nor CA9 genes have been implicated in dental caries before, however, their plausible roles in craniofacial morphogenesis and pH regulation could suggest that they may influence cariogenesis." (PMID 34311721, 2021).
diabetes (1 paper, 2023). "To investigate the potential association between Talin-1 gene expression and diabetes mellitus (DM) in human, we conducted a re-analysis of the single-cell RNA sequencing (scRNA-seq) dataset obtained from human islets in the PANC-DB." (PMID 37903776, 2023). "Hence, our scRNA-seq analysis revealed a substantial upregulation of Talin-1 in patients with diabetes." (PMID 37903776, 2023). "Modulating the Talin-1/Smurf1/Stat3 axis in pancreatic islet β-cells could serve as a promising therapeutic approach for patients with diabetes." (PMID 37903776, 2023). "Collectively, these results further indicate the importance of Talin-1 in controlling β-cell proliferation and glucose homeostasis and may serve as a potential therapeutic target for diabetes milletus." (PMID 37903776, 2023).
Glucose intolerance (1 paper, 2023). Glucose intolerance (GI) can be defined as dysglycemia that comprises both prediabetes and diabetes. "Talin-1 deficiency impairs β-cell proliferation at least in part by decreasing Stat3 protein, resulting in reduced β-cell mass and insulin secretion, and glucose intolerance in mice." (PMID 37903776, 2023). "Collectively, our findings suggest that Talin-1 deficiency reduces insulin expression mainly through inhibiting β-cell proliferation and mass which could contribute to the glucose intolerance of cKO mice." (PMID 37903776, 2023). "Finally, inducible deletion Talin-1 in β-cell causes glucose intolerance in adult mice." (PMID 37903776, 2023). "Here we demonstrate the high expression of Talin-1 in β-cells and that deficiency of Talin-1 reduces β-cell proliferation, which leads to reduced β-cell mass and insulin expression, thus causing glucose intolerance without affecting peripheral insulin sensitivity in mice." (PMID 37903776, 2023). "Additionally, mice with haploinsufficiency of Talin-1 and Stat3 genes, but not that of either gene, in β-cells exhibit significant glucose intolerance and reduced insulin expression, suggesting that both factors function in the same genetic pathway." (PMID 37903776, 2023).
HCMV infection (1 paper, 2014). "The interaction with WAVE2, ABI1, ABI2, NAP1, CYFIP1, and talin-1 were validated in conventional immunoprecipitation experiments when pUL135 was expressed in both isolation and the context of HCMV infection." (PMID 25121749, 2014). "pUL135 is not needed for HCMV to disrupt focal adhesions yet was required for talin-1 to be redistributed to the cell periphery during HCMV infection." (PMID 25121749, 2014).
head and neck cancer (1 paper, 2025). A primary or metastatic malignant neoplasm affecting the head and neck. "Furthermore, hypoxia‐induced HIF1α activation promotes calpain 2, leading to the enzymatic cleavage of talin‐1 and β1 integrin, which facilitates amoeboid migration of breast and head and neck cancer cells." (PMID 40151834, 2025).
Hyperglycemia (1 paper, 2023). An increased concentration of glucose in the blood. "Talin-1 defficiency in β-cells leads to hyperglycemia in mice upon glucose challenge, which is primarily attributed to impaired glucose-stimulated insulin secretion (GSIS) and reduced β-cell mass, rather than peripheral insulin resistance." (PMID 37903776, 2023).
Hyperinsulinemia (1 paper, 2020). An increased concentration of insulin in the blood. "Given the significant reduction of talin-1 reported in the present study, this finding could be related to the previously reported alterations in lamellar IGF-1R during hyperinsulinemia." (PMID 32596266, 2020).
hypertrophic cardiomyopathy (1 paper, 2025). A condition in which the myocardium is hypertrophied without an obvious cause. "Proteomic profiling identified a set of six proteins with predictive value for SCD in patients with hypertrophic cardiomyopathy (HCM): thrombospondin-1 (THBS1), complement C3 (C3), aldolase A (ALDOA), Ras suppressor protein 1 (RSU1), glutathione S-transferase omega 1 (GSTO1), and talin-1 (TLN1)." (PMID 40725061, 2025).
ischemic stroke (1 paper, 2025). A stroke disorder caused by obstruction of blood flow to the brain, due to thrombotic (local blood clot formation) or embolic (due to a blood clot or other material traveling from another site) event. "In a recent study focused on ischemic stroke diagnosis and immune biomarkers identification associated with T cell helper function, TLN1 was discovered as an important marker." (PMID 39951434, 2025).
leukocyte adhesion deficiency (1 paper, 2020). Leukocyte adhesion deficiency (LAD) is a primary immunodeficiency characterized by defects in the leukocyte adhesion process, marked leukocytosis and recurrent infections. "Diseases associated with TLN1 include Leukocyte adhesion deficiency, type I and Leukocyte adhesion deficiency, type Iii." (PMID 32938406, 2020).
liver fibrosis (1 paper, 2025). "Although other E3 ligases may also interact with TLN1, SMURF1 is of particular interest due to its established roles in TGF-β and Hippo signaling—pathways critically involved in MASLD, liver fibrosis, and HCC." (PMID 41284206, 2025).
Lymphatic Metastasis (1 paper, 2022). Transfer of a neoplasm from its primary site to lymph nodes or to distant parts of the body by way of the lymphatic system. "Besides, high expression of TLN1 was detected in chest wall recurrence, lymphatic metastasis, and intestinal metastasis." (PMID 35285795, 2022).
multiple endocrine neoplasia type 2 (1 paper, 2024). Multiple endocrine neoplasia type 2 (MEN2) is a multiple endocrine neoplasia, a polyglandular cancer syndrome characterized by the occurrence of medullary thyroid carcinoma (MTC), pheochromocytoma (PCC), in one variant, primary hyperparathyroidism (PHPT). "Finally, we highlight a talin 1 and 2 (TLN1 and TLN2) PTB binding site in the proto-oncogene tyrosine-protein kinase receptor Ret (RET), which is disrupted by two mutations (L1061P, Y1062A) linked to multiple endocrine neoplasia type 2 and to different types of tumours." (PMID 39009827, 2024).
myalgic encephalomyelitis (1 paper, 2022). "For example, in patients with myalgic encephalomyelitis and chronic fatigue syndrome, which are challenging to diagnose, the amount of EVs in plasma increases, and actin network proteins such as talin-1 and filamin A, which are characteristically encapsulated, may serve as biomarkers." (PMID 36557150, 2022).
oral cancer (1 paper, 2014). "In fact, we observed a decrease in cell adhesion and migration, which strengthen the role talin-1 might play in oral cancer development." (PMID 24858105, 2014).
ovarian endometriosis (1 paper, 2021). A non-neoplastic disorder characterized by the growth of endometrial tissue in the ovaries. "Compared with that in the normal endometrium (2.73 ± 0.80), the Talin-1 protein expression in the eutopic (3.35 ± 0.69) and ectopic endometrium (6.73 ± 2.01) of ovarian endometriosis was significantly increased (P = 0.014; P < 0.001, respectively)." (PMID 33750407, 2021).
peritonitis (1 paper, 2023). Inflammation of the peritoneum (tissue that lines the abdominal wall and covers most of the organs in the abdomen). "In peritoneal neutrophils, T.J.F. Lim and I.H. Su found that TLN1/K2454 trimethylation was induced in vivo during the course of peritonitis." (PMID 37833721, 2023).
psoriasis (1 paper, 2023). An autoimmune condition characterized by red, well-delineated plaques with silvery scales that are usually on the extensor surfaces and scalp. "Among these proteins, well-known circulating markers for psoriasis such as P-selectin (P16109), S100A8 (P05109), S100A9 (P06702), and talin-1 (Q9Y490) were found to be upregulated in patients with psoriasis compared to healthy control." (PMID 36804462, 2023).
uveal melanoma (1 paper, 2021). A melanoma derived from melanocytes of the uveal tract. "In contrast, the most drastic talin-1 downregulation is seen in uveal melanoma (UCS; − 25%) and endometrial carcinoma of the uterine (UCEC; –25%)." (PMID 33431906, 2021).
viral infection (1 paper, 2020). "Integrins play an important role in cell signaling and recent research indicates that Hepatitis B degrades talin 1 to facilitate its replication, but much is still unknown about this protein and viral infection." (PMID 33343631, 2020).
ZIKV infection (1 paper, 2018). "Specifically, we observed that the FMRP targets, FXR2, TLN1, BRD4, and PNPLA6 were elevated at the protein level as a consequence of ZIKV infection." (PMID 30511641, 2018).
cancer (64 papers, 2012 to 2026). A tumor composed of atypical neoplastic, often pleomorphic cells that invade other tissues. "Dysregulation of TLN1 expression is associated with cancer progression, promoting invasion, metastasis, and treatment resistance." (PMID 41148856, 2025). "i) Changes in talin-1 and talin-2 expression levels have been associated with the onset and poor prognosis of several cancers, such as prostate cancer and breast cancer." (PMID 40960860, 2025). "ii) A cancer-associated talin-1 isoform has been identified, causing alteration of the mechanostability of talin-1." (PMID 40960860, 2025). "Cancer-associated Talin-1 mutation and dysregulations induce metastasis by disrupting integrin activity, leading to the loss of cell adhesion and organization." (PMID 37013489, 2023). "The results of several previous studies on other cancers are in line with our findings, indicating that upregulation of talin-1 is significantly associated with cancer progression and worse prognosis." (PMID 37942198, 2023). "Given its functional properties and association with cancer processes, TLN1 is indeed a potential drug for targeted therapy, but more investigation is needed to decipher how drugs should be developed to tackle protein action and/or TLN1 expression." (PMID 35814389, 2022). "Talin-1 also contributes to anoikin resistance, the mechanism by which cancer cells evade apoptosis after the loss of cell–cell adhesion and detachment from the ECM." (PMID 34684727, 2021). "During this study ~ 670 more cancer–associated talin-1 point mutations have been added to the COSMIC database and there are recent studies discussing the connection between talin and cancer." (PMID 33431906, 2021). "As the mutations within the common oncogenes will heavily affect the cell signalling, it is difficult to predict exactly what would be the contribution of these studied talin-1 mutations for the cancer progression in their original context." (PMID 33431906, 2021). "Talin-1 is a key component of the multiprotein adhesion complexes which mediate cell migration, adhesion and integrin signalling and has been linked to cancer in several studies." (PMID 33431906, 2021). "TLN1 is frequently overexpressed in various types of cancer, and serum TLN1 levels have been associated with HCC progression." (PMID 27775586, 2016). "Through a series of computational methods, biochemical and cell biological analysis, results suggested cancer-related point mutations in talin-1 can affect cell behaviour and so may contribute to cancer progression." (PMID 35223494, 2022). "Beyond the FA component, TLN1 is also associated with chemosensitivity to cancer therapy." (PMID 35285795, 2022). "Our findings suggest that cancer related point mutations in talin-1 can affect cell behaviour and so may contribute to cancer progression." (PMID 33431906, 2021). "With the aid of bioinformatic classification, molecular modelling, biochemical analyses and functional cell biology assays, we found that mutations in talin-1 affect cellular processes linked with cancer progression, such as migration, invasion and proliferation." (PMID 33431906, 2021). "Furthermore, TLN1 has been acknowledged as one of the biomarkers of disulfidptosis in some cancers because it could encode actin-related proteins with disulfide bonds elevated in response to glucose scarcity." (PMID 39061076, 2024). "Together, these studies indicate that Talin-1 may serve as a potential diagnostic and prognostic marker of aggressive phenotypes and may represent a potential therapeutic target for various types of cancer." (PMID 25925041, 2015). "In several cancer cell lines, talin-1 is necessary for hyaluronic acid (HA)-induced activation of integrin." (PMID 40362467, 2025). "Expression analyses showed that circRNA_400029 and TLN1 level were significantly elevated in CC tissue and cancer cells, while miR-1285-3p was downregulated." (PMID 41148856, 2025).
cancer (continued). "A panel of Clathrin Heavy Chain (CLTC), Ezrin (EZR), Talin-1 (TLN1), Adenylyl cyclase-associated protein 1 (CAP1), and Moesin (MSN) positive exosomes demonstrated 0.94–0.99 accuracy against other cancers." (PMID 40363817, 2025). "Given the small number of cancer-related deaths or events, a longer follow-up time is necessary to determine the prognostic value of talin-1 expression." (PMID 37942198, 2023). "In this regard, further studies are needed to elucidate these mechanisms and better understand the role of talin-1 in cancer." (PMID 37942198, 2023). "The presence of TLN1 exon 17b in cancer cell lines can thus be detected by conventional RT-PCR, reflected by a clear shift in amplicon size, without the need for RNA-Seq analysis." (PMID 36880935, 2023). "Although exon 17b can be readily detected in many healthy tissues including skin and pancreas, this novel TLN1 exon is significantly enriched in certain molecular cancer subtypes." (PMID 36880935, 2023). "Talin-1 has shown paradoxical expression at the protein level in other malignancies and cancer research." (PMID 37942198, 2023). "Bioinformatic pre-mRNA splicing analysis of pan-cancer RNA-Seq data sets from The Cancer Genome Atlas (TCGA) revealed a robustly transcribed undocumented mRNA sequence in TLN1." (PMID 36880935, 2023). "We initially discovered TLN1 exon 17b through analysis of differential splicing events in cancer tissues." (PMID 36880935, 2023). "The role of Talin-1 dysregulation in cancer has been studied widely; however, a substantial controversy in the literature exists today regarding the regulation of Talin-1 in different cancers." (PMID 37013489, 2023). "Recent studies have indicated that the dysregulation of Talin-1 can lead to cell spreading, migration, and survival, and this has led to an extensive investigation into its role in cancer and other disorders." (PMID 33750407, 2021). "Despite scant evidence for any direct interaction between these miR-200 members and TLN1 thus far, some other miRNAs such as miR-9, miR-124, and miR-330 have been previously reported to target TLN1 in order to regulate its expression in cancer cell." (PMID 34732818, 2021). "The expression of TLN1 and TLN2 was positively associated with CNV in most cancers, except for APBB1IP, RAP1B, and RAP1A." (PMID 33391455, 2021). "Talin-1 is involved in cell adhesion, progression, extravasation, and trans-endothelial migration in cancer." (PMID 34277614, 2021). "The involvement of VAT1, a largely uncharacterized enzyme, has also been reported in the regulation of cancer cell motility and its interaction with Talin-1, a key cytoskeletal protein." (PMID 32867073, 2020). "The expression of talin-1 in NSCLC samples is significantly higher than that in para-carcinoma tissues." (PMID 32742451, 2020). "To date, high TLN1 expression level has been shown to boost migration and invasion of various carcinomas, such as NPC, prostate cancer and glioblastoma, while it showed the opposite effect in hepatocellular carcinoma." (PMID 31068760, 2019). "Previous studies have indicated that Talin-1 plays a role in tumour formation, migration, and metastasis in different types of cancer." (PMID 28251161, 2017). "We found Talin-1 to be highly expressed in HCC cells relative to non-cancer liver epithelial cells and to promote tumor growth and metastasis." (PMID 28099903, 2017). "Studies indicated that Talin-1 is a potential marker for diagnosing cancer at an early stage because its high expression level in serum specimens from cancer patients was sufficient to distinguish them from normal human samples." (PMID 28099903, 2017). "In cell migration and invasion assays, significant reductions in the migration rates of cancer cells were observed in both miR-124 and talin 1 siRNA transfectants compared with the control group." (PMID 25969668, 2015).